KIF5B (kinesin family member 5B)
Description:
Microtubule-dependent motor required for normal distribution of mitochondria and lysosomes. Can induce formation of neurite-like membrane protrusions in non-neuronal cells in a ZFYVE27-dependent manner (By similarity). Regulates centrosome and nuclear positioning during mitotic entry. During the G2 phase of the cell cycle in a BICD2-dependent manner, antagonizes dynein function and drives the separation of nuclei and centrosomes. Required for anterograde axonal transportation of MAPK8IP3/JIP3 which is essential for MAPK8IP3/JIP3 function in axon elongation (By similarity). Through binding with PLEKHM2 and ARL8B, directs lysosome movement toward microtubule plus ends (Probable). Involved in NK cell-mediated cytotoxicity. Drives the polarization of cytolytic granules and microtubule-organizing centers (MTOCs) toward the immune synapse between effector NK lymphocytes and target cells.
Synonyms: UKHC; KNS; KNS1; HEL-S-61; KINH
Tractability: Small molecule: an approved drug acts on it; a structure with a bound ligand is known; a high-quality ligand is known; it has a binding pocket of medium quality. Antibody: UniProt places it where antibodies can reach, with high confidence. PROTAC: UniProt records ubiquitination sites on it; ubiquitination databases record sites on it; its protein half-life has been measured; a small molecule that binds it is known.
Target class: Other cytosolic protein
Gene: Protein-coding gene on chromosome 10 (32,009,014 to 32,056,454, reverse strand). Ensembl gene ENSG00000170759.
Subcellular location: Cytoplasm, cytoskeleton; Cytolytic granule membrane; Lysosome membrane
Subcellular location (Human Protein Atlas): Centriolar satellite; Cytosol; End piece
Pathways (Reactome):
Disease: Signaling by ALK fusions and activated point mutants
Hemostasis: Kinesins
Immune System: MHC class II antigen presentation
Metabolism of proteins: Insulin processing
Signal Transduction: RHO GTPases activate KTN1
Vesicle-mediated transport: COPI-dependent Golgi-to-ER retrograde traffic
Gene Ontology:
Molecular function: cadherin binding; identical protein binding; microtubule binding; microtubule motor activity; protein binding; plus-end-directed microtubule motor activity; ATP binding; protein-containing complex binding
Biological process: centrosome localization; lysosome localization; natural killer cell mediated cytotoxicity; positive regulation of potassium ion transport; positive regulation of protein localization to plasma membrane; regulation of membrane potential; vesicle transport along microtubule; anterograde axonal protein transport; anterograde dendritic transport of neurotransmitter receptor complex; anterograde neuronal dense core vesicle transport; axon guidance; microtubule-based movement; retrograde neuronal dense core vesicle transport; stress granule disassembly; synaptic vesicle transport; positive regulation of synaptic transmission, GABAergic; regulation of modification of synapse structure, modulating synaptic transmission
Cellular component: cytolytic granule membrane; cytosol; lysosomal membrane; membrane; vesicle; kinesin complex; perinuclear region of cytoplasm; axon cytoplasm; ciliary rootlet; cytoplasm; cytoskeleton; dendrite cytoplasm; endocytic vesicle; mitochondrion; neuron projection; phagocytic vesicle; postsynaptic cytosol
Genetic constraint (gnomAD): Loss-of-function variants: 20 observed, 67.07 expected, observed/expected ratio (o/e) 0.3, 90% interval 0.21 to 0.43. The upper end of that interval is the gene's LOEUF score, 0.43, which puts it in group 1 of 6, group 1 being the genes least tolerant of losing a copy. Missense variants: 489 observed, 742.97 expected, observed/expected ratio (o/e) 0.66, 90% interval 0.61 to 0.71. Synonymous variants: 242 observed, 249.54 expected, observed/expected ratio (o/e) 0.97, 90% interval 0.87 to 1.08.
Homologues: Orthologues: chimpanzee KIF5B (99% identical), macaque KIF5B (99% identical), pig KIF5B (99% identical), dog KIF5B (99% identical), mouse Kif5b (97% identical), rat Kif5b (97% identical), guinea pig KIF5B (95% identical), rabbit KIF5B (95% identical), tropical clawed frog kif5b (91% identical), zebrafish KIF5B (87% identical), zebrafish kif5ba (87% identical), Drosophila melanogaster Khc (61% identical). Paralogues in human: KIF5C (75% identical), KIF5A (70% identical), CENPE (26% identical), KIF21A (25% identical), KIF21B (25% identical), KIF27 (25% identical), KIF11 (24% identical), KIF7 (24% identical), KIF13A (23% identical), KIF15 (23% identical), KIF4A (23% identical), KIF4B (23% identical), and 29 more.
Diseases named in the same sentence as KIF5B in open-access papers:
KIF5B is named in the same sentence as 88 diseases in open-access papers, as found by Europe PMC text mining. Sharing a sentence is not in itself a finding about the gene and the disease. The quoted sentences say what the papers report.
lung cancer (38 papers, 2012 to 2025). A malignant neoplasm involving the lung. "Consequently, lung cancer patients with different KIF5B-ALK fusion mutations have demonstrated varying degrees of response to first-generation crizotinib and second-generation TKIs, such as ceritinib and alectinib." (PMID 40852483, 2025). "The principal RET fusion partners in non–small-cell lung cancer (NSCLC) are kinesin family member 5B (KIF5B) (70–90%) and CCDC6 (10–25%), followed by NCOA4-RET, TRIM33-RET, ZNF477P-RET, ERCC1-RET, HTR4-RET, CLIP1-RET fusions (18%)." (PMID 41465145, 2025). "Vepafestinib also inhibited the growth of multiple lung cancer patient-derived cell lines harboring RET fusions with different N-terminal partners (CCDC6, KIF5B, TRIM33) and a RETC634W-mutation-positive MTC cell line." (PMID 37743366, 2023). "Kinesin family member 5B (KIF5B)-RET (70–90%) is the most common RET fusion in lung cancer, and CCDC6-RET (10–25%) also has a high proportion." (PMID 36557971, 2022). "In this report, we describe a patient with PSC harboring a KIF5B-RET gene fusion who was initially diagnosed with stage IVb lung cancer." (PMID 36471407, 2022). "The RET mutation (KIF5B–RET fusion), which is found in 1%–2% of lung cancer patients and is also targetable by multiple treatment modalities, was discovered in one patient by liquid biopsy but missed by tissue biopsy." (PMID 35785173, 2022). "Since identification of the first RET fusion (KIF5B-RET) in lung cancer, significant efforts have been made to identify additional novel RET fusions in NSCLC." (PMID 35957881, 2022). "RET fusions have been identified in 5–10% of papillary thyroid cancers and 1–2% of lung cancers and involve distinct fusion partners, including KIF5B in lung adenocarcinoma and CCDC6 in thyroid and lung cancer." (PMID 35510953, 2022). "For example, KIF5B-RET was highly frequent but almost exclusively found in lung cancers (127/262, 48.5%; Bonferroni’s post-test, P < 0.001)." (PMID 36369474, 2022). "In this trial the response rate varied significantly from 0% in KIF5B-RET rearrangement NSCLCs to 67% in non- KIF5B-RET lung cancers." (PMID 33806299, 2021). "In vitro irradiation with -rays generated KIF5B-RET fusion in lung cells, thus pointing, similar to thyroid cancer, to radiation as a possible risk factor for RET fusion in lung cancer." (PMID 32326537, 2020). "In 2012, the first RET fusion in lung cancer, KIF5B-RET, was reported independently by 4 groups from Korea, Japan (2 groups), and the United States." (PMID 30941048, 2019). "In non-small cell lung cancer (NSCLC), echinoderm microtubule-associated protein-like 4 (EML-4) and kinesin family member 5B (KIF5B) account for the majority of ALK gene rearrangement lung cancer." (PMID 26966027, 2016). "All of these findings corroborate that the KIF5B-RET fusion kinase promotes the growth of lung cancer cells both in vitro and in vivo." (PMID 25047660, 2014). "We aimed to provide a basis for the further development of the therapy for KIF5B-RET positive lung cancer patients." (PMID 25047660, 2014). "The important role of KIF5B-RET-STAT3 in promoting the proliferation of lung cancer cells led us to wonder what would happen after inhibition at any step of these signalings." (PMID 25047660, 2014). "In contrast to 13 fusion partner genes of RET in thyroid carcinoma, only KIF5B-RET, CCDC6-RET, TRIM33-RET and NCOA4-RET have been reported in lung cancer, and KIF5B-RET is the most commonly identified gene fusion in NSCLCs to date." (PMID 25047660, 2014). "Significantly, all these inhibitors reduced the cell proliferation of KIF5B-RET positive lung cancer cells in vitro." (PMID 25047660, 2014). "Our results thus provide possible strategies for the treatment of KIF5B-RET positive lung cancer patients." (PMID 25047660, 2014). "To verify the oncogenic activity of KIF5B-RET kinase in lung cancer cells, we manipulated its expression genetically followed by colony formation and tumor formation assays." (PMID 25047660, 2014).
lung cancer (continued). "Other less common rearrangements detected in lung cancer patients include KIF5B-ALK (kinesin family member 5B-ALK), TFG (trafficking from ER to golgi regulator)-ALK, KLC1 (kinesin light chain-1)-ALK, PTPN3 (protein tyrosine phosphatase non-receptor type 3)-ALK, STRN (striatin)-ALK." (PMID 39457620, 2024). "Several studies have revealed that the KIF5B gene may play an essential role in lung cancer invasion and metastasis." (PMID 35847962, 2022). "Similarly, at least 45 RET fusion partners have been identified in lung cancers, with the most common being kinesin family member 5B (KIF5B)-RET (70-90%) and CCDC6-RET (10-25%)." (PMID 35957881, 2022). "KIF5B gene and MET gene were reported to fuse in lung cancer, which causes elevated tumor growth." (PMID 33204717, 2020). "We demonstrated that the transcription levels of ALK- or RET-fusion partner genes, such as EML4, CCDC6 and KIF5B, were constitutively activated in lung cancer cells, and the expression at the C-terminal region of ALK, RET, or ROS1 was also markedly elevated in each fusion-positive lung cancer cell." (PMID 30943926, 2019). "RET is fused with genes such as KIF5B or CCDC6 in approximately 1% of lung cancers." (PMID 30943926, 2019). "It has been shown that KIF5B-RET fusion kinase promotes cell proliferation of lung cancer, then the phosphorylation levels of proliferation related signaling molecules was investigated by measuring the enforced expression of KIF5B-RET in A549 and Beas-2b cells." (PMID 25047660, 2014). "Strong phosphorylation of STAT3 was presented in KIF5B-RET positive lung cancer cells." (PMID 25047660, 2014). "RT-PCR was used to screen for KIF5B-RET fusions in Chinese lung cancer patients." (PMID 25047660, 2014). "Using lung cancer tissue microarrays containing 1,528 samples, rearrangement of KIF5B was examined by a split FISH assay to discover new fusions, because they previously identified KIF5B-ALK fusions in lung cancer and thus hypothesized that KIF5B might fuse to other kinases in lung cancer." (PMID 30941048, 2019). "Oncogenic PTC/RET translocations detected in thyroid cancer and cell lines are sensitive in vitro and in vivo to RET inhibitors, suggested the possibility that sunitinib, sorafinib, vandetanib, or other RET inhibitors might also be clinically effective in KIF5B/RET lung cancers." (PMID 23342255, 2012). "Until recently, MET fusion, such as KIF5B-MET, MET-ATXN7L1, and HLA-DRB1-MET had mainly been reported in lung cancer." (PMID 36483096, 2022). "In contrast, some of the low frequency fusions, CCDC6-RET in thyroid and NSCLC lung cancer, FGFR2-BICC1 in cholangiocarcinoma, PTPRZ1-MET and KIF5B-RET in non-small cell lung (NSCLC) cancer (≤5 fusions detected) did show linkage to tumour type." (PMID 35984852, 2022). "The first RET gene fusion to be detected in lung cancer involved the 3′-end of RET and the 5′-end of the kinesin family member 5B gene (KIF5B)." (PMID 32397295, 2020). "High expression of KIF5B is observed in breast and skin cancer, and the overexpression of KIF14 promotes the development of retinoblastoma, lung cancer, and breast cancer." (PMID 33585227, 2020). "In a previous report, we detected 15 RET fusion transcripts in cells taken from a lung cancer patient and confirmed five RET fusion partners (KIF5B, CCDC6, TRIM33, NCOA4, and CUX1)." (PMID 27150058, 2016). "Our results have consolidated the role of KIF5B-RET fusion gene in the pathogenesis of NSCLC and identified STAT3 as a key mediator of the transforming activity of KIF5B-RET positive lung cancer cells." (PMID 25047660, 2014). "In contrast, less prevalent actionable fusions exhibited tumour type specificity including CCDC6-RET fusions in thyroid and lung cancer, FGFR2-BICC1 in cholangiocarcinoma, PTPRZ1-MET in glioblastoma, EIF3E-RSPO2 and PTPRK-RSPO3 in colorectal cancer and KIF5B-RET in NSCLC as previously reported." (PMID 35984852, 2022).
lung cancer (continued). "Oncogenic fusions, such as those involving kinases, continue to be discovered (i.e. KIF5B-RET) and may have immediate implications on lung cancer management." (PMID 26934441, 2016). "For example, in a study using a split FISH assay to evaluate 1528 lung cancers, 22 tumors were detected with split RET signals, of which 12 were confirmed as fusions with KIF5B and one with CCDC6 and the remaining nine tumors showed little or no expression of the RET kinase domain." (PMID 25881079, 2015). "Furthermore, we found that KIF5B-RET fusion kinase induced multilevel activation of STAT3 at both Tyr705 and Ser727, and KIF5B-RET-STAT3 signaling related inhibitors repressed the proliferation and tumorigenicity of lung cancer cells significantly." (PMID 25047660, 2014). "KIF5B-RET is reported in a low percentage of lung cancers and is more frequent in non-smokers, in patients with adenocarcinoma, and exists exclusively with other mutations, such as EGFR, Kras, Braf, ErbB2 or EML4/ALK fusions." (PMID 25047660, 2014). "Consistently, when the KIF5B-RET variant 1 and 2 were exogenously expressed in A549 human lung cancer cells, RET Tyr905 was phosphorylated in the absence of serum or GDNF stimulation, indicating an aberrant activation of RET kinase by fusing with KIF5B." (PMID 25047660, 2014). "The most frequent ALK fusion in lung cancer is EML4-ALK (4–7%), and the second is KIF5B-ALK (0.5%)." (PMID 22347464, 2012). "Similarly, KIF5B::RET fusions represent more than 70% of RET alterations in lung cancers; however, none of the RET-rearranged microsatellite-unstable tumors carried this variant." (PMID 37686416, 2023). "As cells with KIF5B/RET fusion gene overexpress the chimeric RET receptor tyrosine kinase and show spontaneous cellular transformation, inhibiting RET receptor tyrosine kinase may suppress tumor progression of KIF5B-RET fusion-positive lung cancer." (PMID 23342255, 2012). "Of the 3 histopathologically confirmed ALK fusion partners in lung cancer, EML4 colocalizes with microtubules and may contribute to the stabilization of microtubules, KIF5B moves on the microtubules as a kinesin heavy chain, and KLC1 binds to kinesin heavy chains as a kinesin light chain." (PMID 22347464, 2012). "The rest of the fusion events, except ALK-EML4 and KIF5B-RET, had not been reported previously, whereas several genes were known to play a role in lung cancer development when considering the gene level separately." (PMID 34599262, 2021). "In lung cancer, 3 fusion partners of ALK have been reported—EML4, TFG, and KIF5B—although the presence of TFG-ALK in lung cancer has not yet been proven with histopathological evidence." (PMID 22347464, 2012). "We developed a 5′-rapid amplification of cDNA ends-based system optimized for FFPE tissues and evaluated this system on a lung cancer tissue with ALK rearrangement and without the 2 known ALK fusions EML4-ALK and KIF5B-ALK." (PMID 22347464, 2012). "Our data suggest that KIF5B-RET promotes the cell growth and tumorigenicity of non-small cell lung cancers through multilevel activation of STAT3 signaling, providing possible strategies for the treatment of KIF5B-RET positive lung cancers." (PMID 25047660, 2014).
lung adenocarcinoma (32 papers, 2012 to 2026). A carcinoma that arises from the lung and is characterized by the presence of malignant glandular epithelial cells. "Adenoviruses encoding Cas9 and sgRNA pairs inducing the Kif5b-Ret and Trim24-Ret rearrangements were intratracheally instilled into mice and yielded lung adenocarcinomas." (PMID 37470475, 2023). "We detected the KRAS and EGFR mutation as well as the KIF5B-RET fusion gene in primary lung adenocarcinomas." (PMID 26268359, 2015). "The mutation KIF5B-RET is the most relevant in lung adenocarcinoma, a subtype of NSCLC." (PMID 30423915, 2018). "Moreover, clinical studies that combine RET inhibitors and EGFR TKIs with other targeted drugs are warranted for the lung adenocarcinoma patients harboring concurrent KIF5B-RET fusion gene and EGFR or KRAS mutations." (PMID 26268359, 2015). "Therefore, screening for the EGFR and KRAS mutations, and ALK and KIF5B-RET translocations should be considered during initial diagnosis of lung adenocarcinomas." (PMID 26268359, 2015). "Currently, approximately 60% of lung adenocarcinomas have now been shown to have mutations (KIF5B-Ret, ROS1, NTRK1, HER2-Neu, to name a few) that may induce and drive these malignancies and the association of TTF-1 status and presence of these driver mutations remains to be elucidated." (PMID 25594059, 2014). "This case report describes a stage IV ALK-rearranged lung adenocarcinoma (LUAD) patient who developed KIF5B-RET fusion-mediated resistance to second-line alectinib therapy." (PMID 40599544, 2025). "As KIF5B is considered a common fusion partner of RET in lung adenocarcinoma, the prediction of our XAI model is appropriate." (PMID 38791993, 2024). "In this case study, a 60-year-old patient diagnosed with stage IV lung adenocarcinoma and carrying a KIF5B-RET fusion gene underwent pralsetinib treatment as the fourth-line therapy." (PMID 40083593, 2024). "A 59-year-old woman with a history of stage IV lung adenocarcinoma harboring a KIF5B-RET fusion presented with disease progression following first-line chemo-immunotherapy." (PMID 39882443, 2024). "We present a case of a lung adenocarcinoma patient harboring a novel kinesin family member 5B (KIF5B)-NTRK1 gene fusion that responds well to entrectinib." (PMID 39590120, 2024). "Herein we present a case involving a female patient who was diagnosed with stage IIIA lung adenocarcinoma and harbored a KIF5B-RET rearrangement based on next-generation sequencing." (PMID 35223529, 2022). "Rebiopsy revealed lung adenocarcinoma with KIF5B-RET fusion and a high level of PD-L1 expression (TPS = 50%)." (PMID 32295619, 2020). "It was consistent with the previous research in lung adenocarcinomas, which found apatinib inhibits cellular invasion and migration by fusion kinase KIF5B-RET via suppressing RET/Src signaling pathway." (PMID 30400838, 2018). "The KIF5B-RET transgenic mice develop lung adenocarcinomas, indicating that RET fusion genes are oncogenic drivers of lung adenocarcinomas." (PMID 29088743, 2017). "We discovered KIF5B-RET fusion genes in 9 (5.8 %) out of 154 patients with lung adenocarcinoma, at a higher frequency than was reported previously." (PMID 26268359, 2015). "In 2012, we first identified the existence of the Kinesin family member 5B (KIF5B)-RET fusion gene in a young male patient with lung adenocarcinoma using whole-genome and transcriptome sequencing analysis." (PMID 26268359, 2015). "The KIF5B-RET fusion gene has been reported to occur in 1–2 % of lung adenocarcinomas; however, adenocarcinomas of other anatomical sites lack this mutation." (PMID 26268359, 2015). "We performed RT-PCR assay for the KIF5B-RET fusion genes in 100 Chinese LAD (Lung adenocarcinoma) patients." (PMID 25047660, 2014).